ASIC1 (acid sensing ion channel subunit 1)
Description:
Forms voltage-independent, pH-gated trimeric sodium channels that act as postsynaptic excitatory receptors in the nervous system, playing a crucial role in regulating synaptic plasticity, learning, and memory. Upon extracellular pH drop this channel elicits transient, fast activating, and completely desensitizing inward currents. Displays high selectivity for sodium ions but can also permit the permeation of other cations. Regulates more or less directly intracellular calcium concentration and CaMKII phosphorylation, and thereby the density of dendritic spines. Modulates neuronal activity in the circuits underlying innate fear (By similarity). [Isoform Asic1a]: Has high selectivity for sodium ions, but can also be permeable to other cations including calcium, lithium and potassium. [Isoform Asic1b]: Produces acid activated currents with a reduced amplitude and inactivates faster. Has high selectivity for sodium ions but also supports a calcium-mediated current which is sustained and maintained as long as acidic conditions are present. Also potentially permeable to lithium and potassium. [Isoform 1]: Has no measurable proton-gated sodium channel activity in vitro.
Synonyms: ACCN2; BNAC2; hBNaC2; ASIC
Tractability: Small molecule: a structure with a bound ligand is known; a high-quality ligand is known; it belongs to a druggable protein family. Antibody: UniProt places it where antibodies can reach, with high confidence; its Gene Ontology location is reachable by antibodies, with high confidence; UniProt predicts a signal peptide or a membrane-spanning region; the Human Protein Atlas places it where antibodies can reach. PROTAC: ubiquitination databases record sites on it; its protein half-life has been measured; a small molecule that binds it is known.
Target class: Ion channel; Ligand-gated ion channel; Acid-sensing ion channel
Gene: Protein-coding gene on chromosome 12 (50,057,548 to 50,083,621, forward strand). Ensembl gene ENSG00000110881.
Subcellular location: Cell membrane; Postsynaptic cell membrane; Cell projection, dendrite; Cell membrane (Isoform Asic1a)
Subcellular location (Human Protein Atlas): Golgi apparatus; Plasma membrane
Pathways (Reactome):
Transport of small molecules: Stimuli-sensing channels
Gene Ontology:
Molecular function: pH-gated monoatomic ion channel activity; protein binding; ligand-gated sodium channel activity; monoatomic cation channel activity; monoatomic ion channel activity; monoatomic ion-gated channel activity; sodium channel activity; transmembrane transporter activity
Biological process: cellular response to pH; sensory perception of sour taste; sodium ion transmembrane transport; sodium ion transport; monoatomic ion transmembrane transport; regulation of postsynapse assembly
Cellular component: glutamatergic synapse; plasma membrane; postsynaptic density membrane; postsynaptic membrane; cell surface; dendrite; membrane; synapse
Genetic constraint (gnomAD): Loss-of-function variants: 21 observed, 64.68 expected, observed/expected ratio (o/e) 0.32, 90% interval 0.23 to 0.47. The upper end of that interval is the gene's LOEUF score, 0.47, which puts it in group 2 of 6, group 1 being the genes least tolerant of losing a copy. Missense variants: 478 observed, 721.93 expected, observed/expected ratio (o/e) 0.66, 90% interval 0.61 to 0.71. Synonymous variants: 258 observed, 288.17 expected, observed/expected ratio (o/e) 0.9, 90% interval 0.81 to 0.99.
Homologues: Orthologues: macaque ASIC1 (100% identical), guinea pig ASIC1 (99% identical), mouse Asic1 (98% identical), chimpanzee ASIC1 (78% identical), pig ASIC1 (78% identical), dog ASIC1 (78% identical), rabbit ASIC1 (77% identical), rat Asic1 (77% identical), zebrafish asic1a (63% identical), Caenorhabditis elegans acd-2 (23% identical), Caenorhabditis elegans mec-10 (21% identical), Drosophila melanogaster Nach (21% identical), and 21 more. Paralogues in human: ASIC2 (59% identical), ASIC4 (49% identical), ASIC3 (49% identical), SCNN1B (24% identical), ASIC5 (24% identical), SCNN1G (24% identical), SCNN1A (23% identical), SCNN1D (22% identical).
Diseases named in the same sentence as ASIC1 in open-access papers:
ASIC1 is named in the same sentence as 86 diseases in open-access papers, as found by Europe PMC text mining. Sharing a sentence is not in itself a finding about the gene and the disease. The quoted sentences say what the papers report.
glioma (19 papers, 2013 to 2025). A benign or malignant brain and spinal cord tumor that arises from glial cells (astrocytes, oligodendrocytes, ependymal cells). "This causes ASIC1 action to be unopposed, and leads to a basally-active cation current which characterizes glioma cells." (PMID 35207041, 2022). "Ross and colleagues identified a role for ASIC1 in glioma cell volume regulation in response to a hyperosmotic solution." (PMID 36768856, 2023). "Glioma patients with high ASIC1 expression had longer survival than those with low ASIC1 expression, pointing to ASIC1 as a potential prognostic biomarker for survival in GBM." (PMID 36768856, 2023). "Previously, we showed that inhibition of the ASIC1 channels by a recombinant analogue of mambalgin-2 from Dendroaspis polylepis controls oncogenic processes in leukemia, glioma, and melanoma cells." (PMID 35837090, 2022). "Further studies in the area of glioma therapeutics should target the role of ASIC1 in OPC to determine the consequent impact on glioma growth." (PMID 35207041, 2022). "For instance, ASIC1 has shown to be expressed in high-grade gliomas and was involved in tumor growth." (PMID 34335195, 2021). "Although there are several studies of ASICs in the pathophysiology of glioma cells, this study uniquely dives deeper into the connection between weak acidosis activated ASIC1 and its effect on the migration of glioma cells." (PMID 34557113, 2021). "The impact of ASICs, particularly ASIC1, in glial cell lines is being further investigated in efforts to reduce glial cell migration, study the potential proliferation effects, and to understand how ASIC1 inhibitors can regulate apoptosis of glioma cells." (PMID 34557113, 2021). "Here, the ASIC1 current plays an important role in glioma cell migration ability, cell cycle progression, and volume regulation." (PMID 27403419, 2016). "High grade gliomas express multiple members of the epithelial sodium channel family, and there is an elevated expression of the acid-sensing ion channel 1 (ASIC1) in glioblastoma cells compared to primary astrocytes." (PMID 25852478, 2015). "Further studies with patient-derived glioma cells using similar techniques could assist in delineating the role of ASIC1 as a therapeutic target across multiple classes of glioblastomas." (PMID 36765806, 2023). "Extracellular microenvironment acidification leads to the recruitment of the ASIC1/ENaC channels into the cell membrane, and the inward cation current mediated by these heteromeric channels may drive the glioma cell growth and migration." (PMID 35837090, 2022). "Further investigation may determine the consequences of cell migration under permanent inhibition of ASIC1 in glioma cells." (PMID 34557113, 2021). "ASIC1 gene expression in glioma cells can predict outcomes of carcinomas as they act as genomic biomarkers; therefore, finding more inhibitors to ASICs may provide potential therapeutic agents to inhibit glioma cell activity." (PMID 34557113, 2021). "Future studies may examine how ASIC1 activated by slow pH changes in high-grade gliomas can affect the tumor growth." (PMID 34335195, 2021). "Extracellular microenvironment acidification leads to the recruitment of the ASIC1/ENaC channels into a cell membrane, and ASIC1a-mediated intracellular cation conductance may drive glioma cell growth and migration." (PMID 32650495, 2020). "This may indicate a role for ASIC1-mediated volume regulation during glioma cell cycle progression." (PMID 36768856, 2023). "Thus, learning more about how and why ASIC1 expression changes in higher-grade gliomas may be vital in determining optimal treatment plans for patients with gliomas." (PMID 34557113, 2021). "Moreover, Ca2+ acts as a second messenger for supporting glioma cell migration, and ASIC1a may be permeable to calcium, suggesting that activated ASIC1 channels allow calcium to permeate and activate CaMKII, thereby regulating ASIC1 channels." (PMID 27403419, 2016).
glioma (continued). "For example, ASIC1 and ASIC2 levels are dramatically increased in glioma, and blockage of cation currents significantly delays the glioma growth metastasis." (PMID 41392978, 2025). "Sheng and colleagues found that ASIC1 was functionally expressed in U87MG and A172 glioma cells." (PMID 36768856, 2023). "Furthermore, expression levels of ASIC1 and ASIC2 correlate with the progression of low-grade gliomas to high-grade glioma; therefore, their inhibition decreases in vitro migration of glioma cells." (PMID 32575381, 2020). "Collectively, the results demonstrate that activation of ASIC1 by weak acidosis in glioma cells A172 and U87MG promotes migration of the cells but not proliferation, while PcTx1 inhibits migration of glioma cells." (PMID 34557113, 2021).
glioblastoma (14 papers, 2013 to 2025). The most malignant astrocytic tumor (WHO grade IV). "ASIC1, a subunit of these channels, has been reported to promote the proliferation of gastric cancer, pancreatic cancer, and glioblastoma." (PMID 40149892, 2025). "Amiloride- and PcTx1-sensitive cation currents in human glioblastoma are produced by mixed ASIC and ENaC components, including ASIC1 and ASIC2." (PMID 29056828, 2017). "In glioblastoma cells, the ASIC1 subunit can form the heterotrimer with the α- and γ-ENaC subunits." (PMID 35837090, 2022). "The study determined the expression of ASIC1 in glioblastoma cell lines, along with the induction of transient inward currents when the pH was dropped from 7.4 to 6.0, suggesting the existence of acid-activated currents in glioblastoma cell lines." (PMID 34557113, 2021). "It has also been shown that knockdown of ASIC1 and ENaC inhibits glioblastoma cell migration." (PMID 24381558, 2013). "Therefore, additional studies might be necessary to further delineate the precise role of ASIC1 in high-grade glioblastoma." (PMID 34557113, 2021). "Similar results were found with ASIC1 knockdowns, using U87MG and primary glioblastoma multiforme cells maintained in primary culture, and may be due to the effect of the ASIC1 knockdown on cell volume recovery via cation currents, because cells cannot divide in a shrunken state." (PMID 27403419, 2016). "A recent study from Dr. Grunder's group reported that glioblastoma stem cell (GSC) lines (R8 and R54) express functional ASIC1 and ASIC3, and their data suggest that expression of ASICs is associated with an improved survival in GSC lines." (PMID 34557113, 2021). "It has previously been reported that ASIC1 and ASIC2 are present in different cell lines derived from glioblastoma patients." (PMID 29057936, 2017). "ASIC1 and ASIC2 have effects on the growth and migration of glioblastoma cells." (PMID 24381558, 2013).
breast carcinoma (12 papers, 2016 to 2024). "For example, the acidic characteristics of tumor microenvironment alters free Ca2+ levelsvia the acid-sensing ion channel 1 (ASIC1), which causes the induction of reactive oxygen species and the activation of NF-κB in breast cancer cells." (PMID 37750331, 2023). "In turn, ASIC1 knock-down inhibits migration of breast cancer cells induced by the cell media acidification." (PMID 34680442, 2021). "The authors also showed that ASIC1 is required for the growth and metastasis of breast cancer in vivo." (PMID 28927426, 2017). "ASIC1 mediates acidosis-induced reactive oxidative species production and NF-κB signaling activation in breast cancer." (PMID 28927426, 2017). "As ASIC1 has been shown to be required for acidosis-induced cell signaling in breast cancer, we determined expressions of ASIC1 in these four prostate cancer cell lines." (PMID 27941930, 2016). "In breast cancer, acid-sensing ion channel 1 (ASIC1) mediates Ca2+ influx." (PMID 29636894, 2018). "We have previously shown that neuron specific acid-sensing ion channel 1 (ASIC1) is expressed in breast cancer, and it is responsible for acidosis-induced cellular signaling through AKT, leading to nuclear factor-κB (NF-κB) activation, and cell invasion and metastasis." (PMID 27941930, 2016). "Moreover, ASICs may have different impact on different tumours, because breast cancer cells also express ASIC1 and alterations in ACCN2 (including amplification, mutations and upregulation) are associated with poor prognosis." (PMID 29057936, 2017).
migraine (12 papers, 2016 to 2024). "As such, we propose that an ASIC3 or combined ASIC1/3 blocker may prove beneficial for the treatment of migraine and that ASIC‐dependent mechanisms may in part underlie the increased susceptibility of migraineurs to NO donors." (PMID 31975427, 2020). "The results shield light on the therapeutic potential of ASIC1 inhibitors as both an acute and prophylactic treatment for migraine." (PMID 34062742, 2021). "We have previously demonstrated the therapeutic potential of the acid‐sensing ion channel (ASIC) blockade in migraine, via an ASIC1 mechanism." (PMID 31975427, 2020). "Most of the work that has been done on ASICs in migraine has focused on ASIC1, namely, ASIC1a, because of its widespread CNS expression." (PMID 29549622, 2018). "The antihypertensive ASIC1 inhibitor amiloride is approved for use in humans, and a few small translational experiments have demonstrated its potential for reducing cutaneous pain and migraine." (PMID 36986537, 2023). "Taken together, available data so far offer a strong indication that the ASIC1 subunit may offer a therapeutic target in migraine." (PMID 36986537, 2023). "Most notably, ASIC1 has recently been shown to be a new potential drug target for migraine." (PMID 29018326, 2017). "This discovery supports the development of specific ASIC3 or combined ASIC1/3 blockers for the treatment of migraine-related pain and suggests a potential role in ASIC-dependent NO-mediated migraine triggering." (PMID 38068897, 2023). "Amiloride was able to reduce aura and headache symptoms in 4 out of 7 patients with otherwise intractable aura, suggesting a possible role for ASIC1 in migraine despite the nonselectiveness of amiloride for these channels." (PMID 29549622, 2018).
epilepsy (6 papers, 2016 to 2025). A brain disorder characterized by episodes of abnormally increased neuronal discharge resulting in transient episodes of sensory or motor neurological dysfunction, or psychic dysfunction. "Second, the high expression of ASIC1 in epilepsy patients was verified in all three sample types, and the phenomenon of its transport from the cytoplasm to the cell membrane/mitochondria was confirmed." (PMID 40677921, 2025). "It suggests that ASIC1 plays a central role in the occurrence and development of epilepsy, and plasma membrane transport may be crucial in this process." (PMID 40677921, 2025). "Finally, although ASIC1 has a limited epileptogenic effect in the acute phase of epilepsy in vivo, selective blockade of ASIC1a using PcTx1 provided significant hippocampal neuroprotection and reduced mitochondrial damage, apoptosis, and cellular autophagy in vitro." (PMID 40677921, 2025).
pancreatic cancer (6 papers, 2017 to 2025). "Collectively, our study highlights a mechanism for acidity-induced EMT in pancreatic cancer cells through ASIC1/3-[Ca2+]i-RhoA axis, which contributed to the metastasis of pancreatic cancer." (PMID 28518134, 2017). "To further demonstrate that ASIC1/3 facilitated aggressive behavior of pancreatic cancer cells in vivo, we next used BxPC-3 cells to establish tumor xenografts with stable knockdown of ASIC1 and ASIC3, respectively." (PMID 28518134, 2017). "This study displayed that acidic pHe significantly increased [Ca2+]i of pancreatic cancer cells in a pH-dependent manner, which was repressed by the inhibition of ASIC1 and ASIC3." (PMID 28518134, 2017). "Indeed, all these channels are involved in acidosis-induced tumor progression: ASIC1 and α-ENaC mediate the epithelial–mesenchymal transition of pancreatic cancer, while ASIC2 promotes the invasion and metastasis of colorectal cancer." (PMID 35837090, 2022). "Similarly, the specific inhibitor for ASIC1, PcTx1 demonstrated inhibitory effects to acidity-promoted invasion and migration of pancreatic cancer cells." (PMID 28518134, 2017). "Together, these findings provide compelling evidence that ASIC1 and ASIC3-[Ca2+]i signaling pathway confers EMT capacity to pancreatic cancer cells in acidity condition." (PMID 28518134, 2017). "Western blot confirmed that the protein of ASIC1 and ASIC3 in pancreatic cancer cell lines was increased compared with normal pancreatic ductal cells." (PMID 28518134, 2017). "The most important new finding in this study is that ASIC1 and ASIC3 transduce the acidic pH to elevation of [Ca2+]i concentration and RhoA activity, promoting EMT of pancreatic cancer cells during acidic microenvironment." (PMID 28518134, 2017). "Given that ASIC1 and ASIC3 are the most sensitive to acidic pHe and function as acidic pH sensors, we first detected the expression of ASIC1 and ASIC3 in pancreatic cancer cells." (PMID 28518134, 2017). "This study reports that ASIC1 and ASIC3 are mainly expressed on membrane of pancreatic cancer cells and upregulated in pancreatic cancer tissues." (PMID 28518134, 2017). "After knockdown of ASIC1 and ASIC3 separately or simultaneously, the acidity-promoted invasion and migration of pancreatic cancer cells were inhibited." (PMID 28518134, 2017). "This study indicates that ASIC1 and ASIC3 senses the variation of acidic microenvironment and transmits this signal into pancreatic cancer cells, resulting in EMT to enhance migration and invasion." (PMID 28518134, 2017). "Together, these results indicate that RhoA is involved in the EMT of pancreatic cancer cells induced by ASIC1/3-[Ca2+]i activation in acidic microenvironment, highlighting that RhoA is a major effector of acidity-induced EMT of pancreatic cancer." (PMID 28518134, 2017). "To further confirm the effects of ASIC1/3 on EMT, we next assessed the expression of ASIC1/3 and EMT marker in pancreatic cancer tissues." (PMID 28518134, 2017). "Taken together, our results provide strong evidence that ASIC1 and ASIC3 promote metastasis of human pancreatic cancer cells in vivo." (PMID 28518134, 2017). "ASIC1 and ASIC3 are mainly expressed on the membrane of pancreatic cancer cells and upregulated in pancreatic cancer tissues, and ASIC1 and ASIC3 promote acid-induced EMT of pancreatic cancer by activating the Ca2+/RhoA pathway, leading to the metastasis of pancreatic cancer." (PMID 38505262, 2024). "Moreover, ASIC1 and ASIC3 were expressed in all 40 pancreatic cancer tissues, but undetected in 6 and 4 out of 40 pancreatic noncancerous tissues, respectively." (PMID 28518134, 2017). "In addition, ASIC1 and ASIC3 contribute to epithelial-mesenchymal transition of pancreatic cancer cells." (PMID 29057936, 2017).